ANKMY2 (ankyrin repeat and MYND domain containing 2)
Description:
May be involved in the trafficking of signaling proteins to the cilia.
Synonyms: DKFZP564O043; ZMYND20; DAF25
Tractability: PROTAC: ubiquitination databases record sites on it; its protein half-life has been measured.
Gene: Protein-coding gene on chromosome 7 (16,599,779 to 16,645,831, reverse strand). Ensembl gene ENSG00000106524.
Subcellular location: Cell projection, cilium
Subcellular location (Human Protein Atlas): Cytosol; Nucleoplasm
Gene Ontology:
Molecular function: protein binding; enzyme binding
Cellular component: cilium
Genetic constraint (gnomAD): Loss-of-function variants: 34 observed, 49.57 expected, observed/expected ratio (o/e) 0.69, 90% interval 0.52 to 0.91. The upper end of that interval is the gene's LOEUF score, 0.91, which puts it in group 3 of 6, group 1 being the genes least tolerant of losing a copy. Missense variants: 545 observed, 518.59 expected, observed/expected ratio (o/e) 1.05, 90% interval 0.98 to 1.13. Synonymous variants: 183 observed, 179.76 expected, observed/expected ratio (o/e) 1.02, 90% interval 0.9 to 1.15.
Homologues: Orthologues: chimpanzee ANKMY2 (99% identical), pig ANKMY2 (95% identical), dog ANKMY2 (94% identical), mouse Ankmy2 (89% identical), macaque ANKMY2 (89% identical), rabbit ANKMY2 (85% identical), rat Ankmy2 (85% identical), guinea pig ANKMY2 (77% identical), tropical clawed frog ankmy2 (71% identical), zebrafish ankmy2a (66% identical), zebrafish ankmy2b (45% identical), Drosophila melanogaster CG8003 (34% identical).
Diseases named in the same sentence as ANKMY2 in open-access papers:
ANKMY2 is named in the same sentence as 7 diseases in open-access papers, as found by Europe PMC text mining. Sharing a sentence is not in itself a finding about the gene and the disease. The quoted sentences say what the papers report.
ciliopathy (1 paper, 2010). A genetic disorder of the cellular cilia or the cilia anchoring structures, the basal bodies, or of ciliary function. "As such, Ankmy2 could participate in phototransduction and be associated with retinopathies, and more generally, could be implicated in other ciliary diseases (ciliopathies)." (PMID 21124868, 2010). "Further studies will be required to experimentally confirm whether Ankmy2 is required for transport of GC1 to the rod outer segment, and to test if Ankmy2 lesions result in retinal disease or a ciliopathy syndrome that includes retinopathies." (PMID 21124868, 2010). "The mammalian ortholog of DAF-25, Ankmy2, interacts with ciliary photoreceptor guanylyl cyclase 1 (GC1), indicating that the role of the MYND domain protein in cilia function is likely to be conserved and potentially relevant to human retinal disease or other ciliopathies." (PMID 21124868, 2010).
cyst (1 paper, 2025). A sac-like closed membranous structure that may be empty or contain fluid or amorphous material. "We found that loss of ANKMY2 suppresses cyst formation in both early postnatal and adult mouse models of PKD." (PMID 41474822, 2025). "In the kidney tubules, lack of ciliary/peri-ciliary adenylyl cyclase signaling from ANKMY2 loss likely suppresses cyst initiation but could be less effective at later stages when cellular cAMP levels rise during cyst progression." (PMID 41474822, 2025). "Similarly, in an adult inducible Pkd1 knockout model, ANKMY2 deficiency reduced cyst burden." (PMID 41474822, 2025). "Our results suggest that ANKMY2-dependent trafficking of adenylyl cyclases to cilia likely promotes compartmentalized ciliary adenylyl cyclase signaling, initiating cyst formation through a mechanism distinct from later cyst progression involving cellular cAMP levels." (PMID 41474822, 2025). "However, the absence of ciliary elongation in Dko mice, irrespective of sex and high cyst burden, demonstrates that increased cellular cAMP levels alone are insufficient to induce ciliary lengthening in the absence of ANKMY2." (PMID 41474822, 2025). "Finally, as ANKMY2 operates the same way in healthy human renal epithelial cells as it does in diseased cyst-lining cells from PKD patients, the ANKMY2-dependent trafficking pathway is not created during ADPKD pathogenesis." (PMID 41474822, 2025).
cystic kidneys (1 paper, 2025). "While the effects on ANKMY2 loss on mature glycoslylated levels of adenylyl cyclases contributes to lack in plasma membrane localization, such reduction was not sufficient to circumvent later changes in adenylyl cyclase/cAMP signaling in cystic kidneys from Pkd1 loss." (PMID 41474822, 2025).
retinal disease (1 paper, 2010). "Interestingly, GC1 and the nuclear hormone receptor Nr2e3 shown to regulate Ankmy2 expression in mouse retina both harbor mutations in patients with retinal disease." (PMID 21124868, 2010).
ANKMY2 also shares sentences with these, for which no sentence is quoted: polycystic kidney disease (2 papers); Obesity (1); retinopathies (1).